MRGPRX4 (MAS related GPR family member X4)
Description:
G protein-coupled receptor for bile acids, which is specifically expressed in sensory neurons of dorsal root ganglion and is involved in itch perception. Activated by bile acids, such as deoxycholate, chenodeoxycholate, taurocholate, taurodeoxycholate and taurodeoxycholate. Has a preference for 3-sulfated bile acids, such as deoxycholate 3-sulfate, glycoursodeoxycholate 3-sulfate and tauroursodeoxycholate 3-sulfate, which are present at high level in cholestatic patients with itch symptoms. Bile acid-binding causes a conformation change that triggers signaling via guanine nucleotide-binding proteins (G proteins) and modulates the activity of downstream effectors. MRGPRX4 is coupled to G(q)/G(11) G alpha proteins and activates phospholipase C-beta, releasing diacylglycerol (DAG) and inositol 1,4,5-trisphosphate (IP3) second messengers that modulate the activity of phosphatidylinositol 3-kinase and promote the release of Ca2+ ions from intracellular stores, respectively.
Synonyms: MRGX4; SNSR6; GPCR
Tractability: Small molecule: a structure with a bound ligand is known; it belongs to a druggable protein family. Antibody: UniProt places it where antibodies can reach, with medium confidence; UniProt predicts a signal peptide or a membrane-spanning region; its Gene Ontology location is reachable by antibodies, with medium confidence. PROTAC: a small molecule that binds it is known.
Target class: Family A G protein-coupled receptor; Membrane receptor
Gene: Protein-coding gene on chromosome 11 (18,172,837 to 18,174,280, forward strand). Ensembl gene ENSG00000179817.
Subcellular location: Cell membrane
Gene Ontology:
Molecular function: G protein-coupled bile acid receptor activity; protein binding; G protein-coupled receptor activity; transmembrane signaling receptor activity
Biological process: phospholipase C-activating G protein-coupled receptor signaling pathway; sensory perception of itch; G protein-coupled receptor signaling pathway; adenylate cyclase-activating G protein-coupled bile acid receptor signaling pathway; adenylate cyclase-modulating G protein-coupled receptor signaling pathway
Cellular component: plasma membrane; membrane
Genetic constraint (gnomAD): Loss-of-function variants: 13 observed, 18.4 expected, observed/expected ratio (o/e) 0.71, 90% interval 0.46 to 1.12. The upper end of that interval is the gene's LOEUF score, 1.12, which puts it in group 4 of 6, group 1 being the genes least tolerant of losing a copy. Missense variants: 399 observed, 417.87 expected, observed/expected ratio (o/e) 0.95, 90% interval 0.88 to 1.04. Synonymous variants: 192 observed, 181.07 expected, observed/expected ratio (o/e) 1.06, 90% interval 0.94 to 1.2.
Homologues: Orthologues: chimpanzee MRGPRX4 (98% identical), macaque MRGPRX4 (80% identical), dog MRGPRX (54% identical), rabbit MGRG2 (54% identical), rat Mrgprx3 (50% identical), mouse Mrgprx1 (50% identical), mouse Mrgprx2 (49% identical), rat Mrgprx1 (49% identical), mouse Mrgpra9 (49% identical), mouse Mrgprb2 (49% identical), mouse Mrgpra3 (49% identical), mouse Mrgpra1 (48% identical), and 16 more. Paralogues in human: MRGPRX3 (82% identical), MRGPRX1 (79% identical), MRGPRX2 (63% identical), MRGPRD (38% identical), MAS1 (33% identical), MAS1L (33% identical), MRGPRE (32% identical), MRGPRF (32% identical), MRGPRG (29% identical), GPR152 (22% identical).
Diseases named in the same sentence as MRGPRX4 in open-access papers:
MRGPRX4 is named in the same sentence as 10 diseases in open-access papers, as found by Europe PMC text mining. Sharing a sentence is not in itself a finding about the gene and the disease. The quoted sentences say what the papers report.
itch (6 papers, 2019 to 2024). "Overall, our study demonstrates that MRGPRX4 recognizes a variety of phosphate-modified medications, potentially explaining the mechanism by which these compounds cause bothersome pruritus." (PMID 38718132, 2024). "Bile acids or other MRGPRX4 specific agonist induced itch in human subjects, providing a promising cause of OCA induced-pruritus." (PMID 32477115, 2020). "However, our findings illuminate a completely different mechanism for phosphor-drug-induced itch: instead of triggering an allergic reaction, these drugs cause itch by directly activating MRGPRX4 in itch-sensing neurons." (PMID 38718132, 2024). "In addition, certain drugs such as nateglinide, a potassium ATP channel blocker used for treatment of type 2 diabetes, are hypothesized to cause pruritus and urticarial rash by activating MRGPRX4 as an off-target side effect." (PMID 37003505, 2023). "The MRGPR antagonist for treating pruritus also targets a specific bile acid-regulated receptor, MRGPRX4, that is activated by bile acids and bilirubin." (PMID 39404413, 2024). "Together, these findings suggest that MRGPRX4 mediates phospho-drug evoked itch and provide a potential therapeutic target to reverse this unintended side effect." (PMID 38718132, 2024). "Bile acids elicited Ca2+ responses in cultured hDRG neurons, and bile acids or a MRGPRX4 specific agonist induced itch in human subjects." (PMID 31500698, 2019). "This could illuminate the role of MRGPRX4-mediated pruritus in other pathophysiological processes, perhaps providing explanations for this primate-specific phospho-sensing phenomenon." (PMID 38718132, 2024). "In addition, intradermal injection of both bile acids and the MRGPRX4-specific agonist nateglinide induce detectable itch in human subjects, and this bile acid-induced itch is histamine-independent." (PMID 31500698, 2019). "Although the natural ligand(s) for MRGPRX4 have not yet been identified, it is of interest that the MRGPRX4 agonist Nateglinide, a drug used to treat Type 2 diabetes, has been reported to have pruritus as a side effect." (PMID 30768591, 2019).
cholestasis (2 papers, 2019 to 2021). Impairment of the bile flow caused by obstruction within the liver, or outside the liver in the bile duct system. "From these results, the authors suggest that high serum bilirubin levels are involved in cholestasis-associated pruritus by binding to MRGPRX4 on sensory neurons." (PMID 33791327, 2021). "Scratch activity was found to be increased in mice expressing MRGPRX4 compared to control animals, but only during the first 2 days of cholestasis, suggesting that this signaling undergoes fairly rapid desensitization." (PMID 33791327, 2021). "However, DC, which showed to be the most potent ligand for MRGPRX4 among all tested bile salts, was not present in a different concentration in plasma of itchy vs. non-itchy patients with cholestasis." (PMID 33791327, 2021).
diabetes (2 papers, 2019 to 2023). "Interestingly, the nateglinide, a FDA approved drug for the treatment of diabetes, previously reported as MRGPRX4 agonist and has itch side effect, —but not vehicle—induced a robust itch sensation in healthy subjects (Figure 6a1, a2)." (PMID 31500698, 2019). "Dose-response curves for the known MRGPRX4 agonists DCA, TDCA, and UDCA were compared with that of the diabetes drug nateglinide." (PMID 37003505, 2023).
Cholestatic liver disease (1 paper, 2021). "Besides FXR, secondary BAs strongly activate two GPCRs, TGR5 and MRGPRX4, both associated with itch in cholestatic liver disease." (PMID 33895309, 2021).
liver diseases (1 paper, 2019). "Elevated bile acids are correlated with the occurrence of itch among patients with liver disease and are sufficient to activate MRGPRX4." (PMID 31500698, 2019). "(e–f) Left, Ca2+ responses in MRGPRX4-expressing HEK293T cells induced by application of a mixture of artificial bile acids derived from itchy patients with liver diseases and healthy subjects." (PMID 31500698, 2019). "For DCA, the most potent ligand for MRGPRX4 among all tested bile acids, we did not see the significant difference between itchy and non-itchy patients with liver diseases, suggesting it is not the major contributor for cholestatic itch under pathological conditions." (PMID 31500698, 2019).
melanoma (1 paper, 2026). A malignant, usually aggressive tumor composed of atypical, neoplastic melanocytes. "MRGPRX4 promotes melanoma cell proliferation and invasion through basal, ligand-independent, PI3K-AKT-MAPK activation." (PMID 42282710, 2026). "MRGPRX4 is upregulated in melanoma and is confined to invasive, neural-crest-like and pre-EMT states associated with dedifferentiation and therapy resistance." (PMID 42282710, 2026). "Pharmacologic MRGPRX4 inhibition suppresses basal signaling and limits melanoma growth and invasion." (PMID 42282710, 2026). "In sum, melanoma exploits MRGPRX4 to acquire an invasive and immunosuppressive phenotype, nominating this somatosensory GPCR as a promising therapeutic target." (PMID 42282710, 2026). "Ectopic MRGPRX4 expression in mouse melanocytes drives 100% penetrant, highly metastatic melanoma, demonstrating oncogenic behavior." (PMID 42282710, 2026). "Comparing transcptomics of MRGPRX4-driven tumors shows a broad overlap with BRAF/NRAS-driven tumors; however, the MRGPRX4 model also enriches an ECM-rich, invasive neural crest-like melanoma state." (PMID 42282710, 2026).
tumor (1 paper, 2026). "MRGPRX4 further remodels the tumor microenvironment toward an immunosuppressive, checkpoint-high state enriched in suppressive myeloid cells." (PMID 42282710, 2026).
MRGPRX4 also shares sentences with these, for which no sentence is quoted: allergic reaction (1 paper); glioblastoma (1); Type 2 diabetes (1).